Y_RNA (Y RNA )
Gene: Miscellaneous RNA gene on chromosome 19 (12,088,245 to 12,088,346, reverse strand). Ensembl gene ENSG00000199444.
Homologues: Orthologues: chimpanzee Y_RNA (99% identical), macaque Y_RNA (92% identical). Paralogues in human: Y_RNA (88% identical), Y_RNA (87% identical), RNY3 (86% identical), Y_RNA (86% identical), Y_RNA (85% identical), RNY3P1 (84% identical), Y_RNA (84% identical), RNY3P16 (83% identical), RNY3P2 (83% identical), Y_RNA (83% identical), RNY3P14 (82% identical), Y_RNA (82% identical), and 94 more.